CD4 (CD4 molecule)
Diseases named in the same sentence as CD4 in open-access papers (continued):
Sharing a sentence is not in itself a finding about the gene and the disease.
HIV-1 infection (continued). "HIV-1 infection is associated with an early and profound depletion of mucosal memory CD4+ T cells, a population that plays an indispensable role in the regulation of isotype switching and transepithelial transport of antibodies." (PMID 28125732, 2017). "HIV-1 infection is characterized by the loss of number and dysfunction of CD4+ T cells and exhibits remarkable differences in clinical outcomes of treatment-naïve individuals." (PMID 28222782, 2017). "In a gene expression analysis performed to identify novel gene modulations associated with cell cycle dysregulation during HIV-1 infection in CD4+ T cells, we observed down-regulation of the cyclin F gene (CCNF)." (PMID 28184007, 2017). "The susceptibility of other myeloid cells to HIV-1 infection appears modulated by surface CD4 expression levels." (PMID 29301198, 2017). "Until recently, CD4 and chemokine receptors were the major cellular molecules associated with HIV-1 infection." (PMID 29123518, 2017). "A hallmark of HIV-1 infection is the continuously declining number of the virus’ predominant target cells, activated CD4+ T cells." (PMID 28264054, 2017). "In the study, we demonstrated the dynamics of IFN lambdas and the related genes and proteins in JAK-STAT pathway in acute and chronic HIV-1 infection, and we analyzed their association with CD4+ T-cell counts and HIV-1 viral loads." (PMID 28623917, 2017). "We previously showed that commensal E.coli-associated enhancement of productive HIV-1 infection of LP CD4 T cells was dependent on the presence of LP mDC and was, in part, mediated through an MHC-Class II dependent mechanism." (PMID 26762145, 2016). "Several studies have focused on the effect of primary HIV-1 infection (PHI) on CD4+ T cells in gut-associated lymphoid tissue (GALT) as a defining event in the pathogenesis of eventual chronic HIV-1 infection (CHI) [reviewed in Ref." (PMID 27822211, 2016). "The reduced susceptibility of MDDC from HICs to HIV-1 infection is in agreement with previous studies showing a reduced permissiveness to HIV-1 of CD4+ T cells and macrophages from the same patients." (PMID 27505169, 2016). "We previously showed that the increased susceptibility of LP CD4 T cells to HIV-1 infection following exposure to E. coli was linked to increased CD4 T cell activation and proliferation." (PMID 26762145, 2016). "Acute human immunodeficiency virus type 1 (HIV-1) infection presents with a dramatic loss of CD4+ T cells, which is accompanied by the production of large quantities of cytokines." (PMID 27279606, 2016). "CEM-5.25 cells are a human CD4 T cell line that are susceptible to HIV-1 infection and contain an integrated HIV-1 Long terminal repeat-Green fluorescent protein (LTR-GFP) reporter cassette." (PMID 27010978, 2016). "TST molecular profiling categorised different mechanisms of immunological dysfunction in HIV-1 infection beyond the effects on CD4 T cells, each associated with increased risk of TB disease and amenable to host-directed therapies." (PMID 26986567, 2016). "Taken together, the let-7i induced IL-2 has a protective effect against CD4+ T cell apoptosis, especially protects cells from the cytotoxicity caused by HIV-1 infection." (PMID 27145859, 2016). "Given that let-7i is a positive regulator of IL-2 gene transcription, it is possible that suppression of let-7i contributes to the CD4+ T cell death caused by HIV-1 infection." (PMID 27145859, 2016). "To identify possible reasons for these differences in clinical progression, we performed comprehensive phenotypic analyses of CD4+ T cells from uninfected young and elderly individuals, and examined their susceptibility to HIV-1 infection and programmed death." (PMID 26452480, 2015).
HIV-1 infection (continued). "HIV-1 infection causes a chronic viral infection that results in selective CD4+ T cell depletion which has a major impact on lymphocytes in the gastrointestinal tract." (PMID 26635799, 2015). "The full elucidation of the mechanism of Nef- and activation-independent CD4+ T cell loss will be important for complete understanding of CD4+ T cell loss in R5-tropic HIV-1 infection." (PMID 26169178, 2015). "Most notably, both advancing age and HIV-1 infection are associated with an increased frequency of memory CD4+CD45RA−CD45RO+ T cells as well as expanded CD4+CD57+ and CD8+CD57+ T cell populations." (PMID 26204934, 2015). "On the one hand, increased levels of T cell activation and CXCR4 cell surface expression together with reduced CD4 expression levels render CD4+ T cells from the elderly highly susceptible to HIV-1 infection and replication." (PMID 26452480, 2015). "CXCR5+PD-1++ CD4+ T cells were the most susceptible to HIV-1 infection (81%) compared to other subsets (second row, far right panel)." (PMID 26034905, 2015). "The IC50 values for cell free, IFN-α-DC or LPS-DC-associated HIV-1 infection of CD4+ T cells were 0.171 ± 0.047, 0.307 ± 0.039 and 0.467 ± 0.117 μg/ml, respectively." (PMID 25760631, 2015). "To identify reasons for the high susceptibility of CD4+ T cells from the elderly to HIV-1 infection, we examined the cell surface expression levels of the primary CD4 receptor and the CCR5 and CXCR4 co-receptors, needed for HIV-1 entry." (PMID 26452480, 2015). "Future investigations will pursue understanding the long-elusive mechanism behind the fundamental phenomenon of CD4+ T cell loss during HIV-1 infection." (PMID 26169178, 2015). "As alluded above, progressive HIV-1 infection is associated with the progressive decrease of CD4+ T cells both in number and in function, but also, as recently shown, with continuous chronic inflammation, is initiated by a burst of pro-inflammatory cytokines." (PMID 29061947, 2015). "In advanced stage of HIV-1 infection, patients become more vulnerable to opportunistic infections concurrent with progressive loss of CD4+ T-cells compared to those in early or intermediate stages." (PMID 26492336, 2015). "Latent reservoirs including resting CD4+ T cells, monocyte/macrophage lineage, microglia, and gut-associated lymphoid tissue macrophages are the main obstacle in the race for a cure of HIV-1 infection." (PMID 26405463, 2015). "The percentages of cytotoxic NK cells was found to be associated positively with the CD4 counts in early as well as late HIV-1 infection (r = 0.502, p = 0.002)." (PMID 24904577, 2014). "The numbers of CD4+ T lymphocytes in the human body are maintained constantly by homeostatic mechanisms that failed during HIV-1 infection, resulting in progressive loss of CD4+ T cells mainly via apoptosis." (PMID 24714696, 2014). "The hallmark of HIV-1 infection is the loss of CD3+CD4+ T cell counts correlating with increases in both virus load and disease progression." (PMID 24454311, 2014). "These antibodies strongly suggest vigorous CD4 T cell help for B-cell responses, consistent with the greatly increased numbers of GCs associated with HIV-1 infection." (PMID 25610441, 2014). "The clinical course of HIV-1 infection is characterized by a symptomatic acute phase, followed by an asymptomatic period with ongoing viral replication and gradual loss of CD4 T cells." (PMID 25047784, 2014). "Our investigations started from the observation that unstimulated CD4+ T lymphocytes became susceptible to HIV-1 infection upon trans-well co-culture with F12/Hut-78 cells." (PMID 24924541, 2014). "We concluded that the exosome-dependent activation of CD4+ T lymphocytes rendered them susceptible to productive HIV-1 infection." (PMID 24924541, 2014). "T cell exhaustion in HIV-1 infection is associated with elevated expression of PD-1 on CD4+ and CD8+ T cells." (PMID 24626392, 2014).
HIV-1 infection (continued). "In order to investigate the physiological relevance of CD4 association to DRM for HIV-1 infection, we used our dual-expression system to knock-down CD4, and also simultaneously expressed CD4 mutants known to have reduced association with DRM." (PMID 24465876, 2014). "HIV-1 infection leads to chronic immune activation characterized by increased T cell activation and exhaustion, elevated levels of sCD14 and a partial loss of CD4 T cells, DCs, iNKT cells, and Tregs." (PMID 25566250, 2014). "This increased proliferation begins at the earliest stages of primary HIV-1 infection and is associated with a CD4 response to viral antigens." (PMID 25610441, 2014). "Exosomes released by cells expressing a defective HIV-1 genome activate bystander, resting CD4+ T lymphocytes and render them susceptible to HIV-1 infection." (PMID 24924541, 2014). "Human immunodeficiency virus type 1 (HIV-1) infection inevitably causes the exhaustion of CD4+ T lymphocytes largely due to apoptosis." (PMID 24714696, 2014). "HIV-1 infection results in the lysis of T lymphocytes (CD4+ T and CD8+ T cells) leading to their depletion, a hallmark of HIV-1 pathogenesis." (PMID 26056579, 2014). "This poses an even greater challenge in progressive HIV-1 infection, where chronic viral replication and immune activation contribute to profound CD4+ T cell loss." (PMID 24498287, 2014). "HIV-1 infection causes severe CD4+ T cell depletion in gut-associated lymphoid tissues (GALTs), resulting in severe defects in intestinal epithelial barrier function and integrity." (PMID 24516541, 2014). "Early HIV-1 infection causes massive CD4+ T cell death in the gut and translocation of bacteria into the circulation." (PMID 24495380, 2014). "Other current guidelines recommend treatment of HIV-1 infection in all patients with CD4 <350 cells/μL and with higher CD4 counts in patients with other risk factors, such as hepatitis co-infections, pregnancy or older age, or to prevent HIV-1 transmission." (PMID 25054884, 2014). "We next performed ex vivo experiments based on fusion assays using reconstituted CD4+ T cells to examine the susceptibility to R5 HIV-1 infection." (PMID 23301078, 2013). "Untreated HIV-1 infection is characterized by continuous viral replication that drives CD4+ T cell loss and predicts disease progression." (PMID 23803414, 2013). "While CD4+ T cells from both species are equally susceptible to HIV-1 infection, chimpanzee cells survive better, suggesting a cell-intrinsic difference." (PMID 22945238, 2013). "MDMs are susceptible to HIV-1 infection as they express both CD4 and the co-receptors CCR5 and CXCR4." (PMID 24330394, 2013). "In the majority of the EC population, the spontaneous control of HIV-1 infection is associated with higher levels of CD4+ T cells (average of 750 cells/ml) than viremic and therapy-treated HIV+ individuals, and slightly lower than uninfected subjects." (PMID 23577012, 2013). "In conclusion, the cortical actin density differentially affects the susceptibility to HIV-1 infection in naïve and memory CD4+ T cells by modulating the efficiency of HIV antigen internalization." (PMID 24244453, 2013). "In this regard, CD4 + T cells are the first choice; they are the major cell type amongst all the susceptible targets and reservoirs of HIV-1 infection." (PMID 23635305, 2013). "Pathogenic HIV-1 infections are characterized by a generalized immune activation with concomitant CD4+ T cell depletion and the failure to effectively control viral replication." (PMID 24130482, 2013). "We observed that HLA-G+ CD4 Treg were significantly more susceptible to HIV-1 infection than autologous HLA-G− CD4 T cells; this was true both for in vitro activated cells and for cells directly infected ex-vivo." (PMID 23382678, 2013). "B cells have also been implicated as intermediaries in enhanced HIV-1 infection of CD4+ T cells by macrophages." (PMID 24278768, 2013).
HIV-1 infection (continued). "Two studies demonstrated that peripheral blood mononuclear cells and CD4+ T-lymphocytes from AGS patients are more susceptible to HIV-1 infection in vitro compared to healthy donors' cells." (PMID 24523981, 2013). "Studies have indicated that destruction of the CD4+ cell pool by HIV-1 infection increases susceptibility of the host to other infectious diseases." (PMID 23849678, 2013). "HIV-1 infection is normally characterized by sustained viral replication and a progressive loss of CD4+ T cells, leading to AIDS." (PMID 23516360, 2013). "Upon co-stimulation with CD3/CD28 antibodies, activated CD4 + T cells were found to lose their susceptibility to HIV-1 infection, exhibiting an induced resistant phenotype." (PMID 23635305, 2013). "A hallmark of HIV-1 infection is the gradual loss of both CD4+ T cells and CD8+ T cells that has been associated with disease progression." (PMID 24130482, 2013). "Nef also promotes polyclonal B cell activation and increases CD4 T cell susceptibility to HIV-1 infection by inducing macrophages to secrete pro-inflammatory cytokines." (PMID 24151490, 2013). "P. falciparum malaria causes increased CD4+ cell activation, increasing the number of susceptible target cells for HIV-1 infection, potentially resulting in increased HIV-1 RNA levels and continued new infection of susceptible activated CD4+ cells." (PMID 23327493, 2013). "The major hallmark of HIV-1 infections includes the destruction or depletion of the total body of helper CD4+ T-lymphocytes, both naïve (CD45RA+) and memory cells (CD4RO+), and a subsequent loss of immune competence." (PMID 23849678, 2013). "In a primate model of HIV-1 infection, we observed that increased IFNα was associated with low peak viral loads in early infection, but high viremia and decreased CD4+ T cell counts during chronic infection." (PMID 24130482, 2013). "We had previously found that HIV-1 infection was associated with an increase in circulating CD4+ T-cells that contained perforin." (PMID 23630526, 2013). "Though these phenotypic indices of activation predict outcome in untreated HIV-1 infection, it is likely that T cell turnover is more closely linked to death of CD4+ T cells." (PMID 24367599, 2013). "The expression of the chemokine receptors CCR5 and CXCR4 on the surfaces of CD4+ T-lymphocytes, which have been stimulated by Th2 cytokines, make these cells more susceptible to HIV-1 infection." (PMID 23849678, 2013). "In this study we analyzed the direct effect of mycobacterial cell-wall associated glycolipids in HIV-1 infection of primary CD4+ T cells." (PMID 24282561, 2013). "A potential problem with directly comparing CD4 T-cells from EC to CD4 T-cells from progressors is the effect of chronic HIV-1 infection associated with increased rates of activation." (PMID 23630526, 2013). "HIV-1 infection is characterized by a rapid Th17 cell depletion associated with an expansion of Tregs owing to cellular immune activation and/or low CD4+ T-cell counts." (PMID 24147117, 2013). "These initial studies in LCMV infection were later extended to HIV infection and IL-21-producing CD4 T cells were associated with improved control of HIV-1 infection and preserved CD8 T cell function in humans." (PMID 23717308, 2013). "Disturbances in differentiation and function of B cells characterize HIV-1 infection, and mostly, these impairments are correlated to the loss of CD4+ T cells and the increase of HIV-1 load." (PMID 22474482, 2012). "It has been known for over two decades that resting CD4+ T-cells are refractory to HIV-1 infection, but the underlying mechanisms are not fully understood." (PMID 23092163, 2012). "Several studies report that CD4+ lymphopenia driven by HIV-1 infection or bone marrow transplantation and idiopathic CD4+ T lymphopenia are often associated with increased serum levels of IL-7." (PMID 22474482, 2012).
HIV-1 infection (continued). "CUL5 polymorphisms in African Americans have been associated with more rapid CD4+ T cell loss following HIV-1 infection." (PMID 23217182, 2012). "In conclusion, we found that a high CCR5 density on CM CD4+ T cells in acute HIV-1 infection is mostly associated with rapid disease progression." (PMID 23185351, 2012). "Here, we evaluated the role of Vpr during infection of highly permissive peripheral blood mononuclear cells (PBMCs) and CD4+ T-cells and compared it to that of monocyte-derived dendritic cells (MDDCs), which are less susceptible to HIV-1 infection." (PMID 22570689, 2012). "Although only a small percentage (<2%) of CD4+ T-cells co express Gb3 we nevertheless, determined the effect of VT on activated PBMCs and their susceptibility to HIV-1 infection." (PMID 23242319, 2012). "Consistent with our previous results, WT HIV-1 infection efficiently decreased (P<0.05) surface CD4 expression in DCs relative to DCs infected with Nef-mutated viruses at 5 dpi." (PMID 22479639, 2012). "HIV-1 infection of hPBMC SCID mice leads to loss of CD4+ T cells, the primary consequence of HIV-1 infection in humans." (PMID 22427811, 2012). "Chronic immune activation, a hallmark of HIV-1 infection, has been associated with disease progression and has even been put forward as a stronger predictive factor for progression than CD4 T cell count or viral load." (PMID 22970212, 2012). "In fact, strong virus-specific CD4+ T-cell responses have been associated with natural control of HIV-1 infection and cytotoxic CD4+ T cells were shown to suppress viral replication in both SIV and HIV-1-infected cells." (PMID 23028895, 2012). "Altogether, this study shows that the inflammatory profile in primary HIV-1 infection is associated with T cell activation levels and CD4+ T cell counts at set-point." (PMID 23056251, 2012). "In this study, we investigated the role of HIV-1 Nef in DC-mediated viral transmission and HIV-1 infection of primary CD4+ T cells using WT HIV-1 and HIV-1 expressing mutated Nef proteins." (PMID 22479639, 2012). "Here we investigated the role of HIV-1 Nef in DC-mediated viral transmission and HIV-1 infection of primary CD4+ T cells using wild-type HIV-1 and Nef-mutated viruses." (PMID 22479639, 2012). "High plasma viremia in HIV-1 infection is associated with rapid CD4 cell decline and faster disease progression." (PMID 23171203, 2012). "It was found that cervical tissue is particularly rich in CCR5-expressing CD4 lymphocytes, which make this tissue potentially more susceptible to R5 HIV-1 infection than lymphoid tissue." (PMID 21284905, 2011). "During primary HIV-1 infection, the number of CD4+ T cells declines in association with high viremia levels, before the onset of antiviral immune response." (PMID 21994747, 2011). "Another cystatin member, cystatin B, has been reported to be associated with higher susceptibility of monocyte-derived macrophages to CD4-dependent HIV-1 infection when compared to placental macrophages." (PMID 21541353, 2011). "The patient's CD4+ T cells are fully susceptible to HIV-1 infection, and he has low titers of neutralizing antibodies to heterologous and autologous HIV-1 isolates." (PMID 22141397, 2011). "We have re-evaluated the role of the PWWP domain of LEDGF/p75 in HIV-1 infection using human CD4+ LEDGF/p75-deficient cells." (PMID 21510906, 2011). "Since the level of central memory CD4+ T cell loss was similar at these timepoints, this suggest that the early immune response to HIV-1 infection is likely to be an important factor in determining the clinical course of disease." (PMID 21464951, 2011). "α4β7 can be engaged by HIV-1 on the cell-surface and CD4+ T cells expressing high levels of this integrin (α4β7high) are particularly susceptible to HIV-1 infection." (PMID 21738472, 2011).